HPX (hemopexin)
Description:
Binds heme and transports it to the liver for breakdown and iron recovery, after which the free hemopexin returns to the circulation.
Synonyms: HX
Tractability: Antibody: its Gene Ontology location is reachable by antibodies, with high confidence; UniProt places it where antibodies can reach, with medium confidence; UniProt predicts a signal peptide or a membrane-spanning region. PROTAC: its protein half-life has been measured.
Gene: Protein-coding gene on chromosome 11 (6,431,006 to 6,442,617, reverse strand). Ensembl gene ENSG00000110169.
Subcellular location: Secreted
Pathways (Reactome):
Vesicle-mediated transport: Scavenging of heme from plasma
Gene Ontology:
Molecular function: protein binding; heme transmembrane transporter activity
Biological process: heme metabolic process; heme transport; intracellular iron ion homeostasis
Cellular component: blood microparticle; extracellular exosome; extracellular matrix; extracellular region; endocytic vesicle lumen
Genetic constraint (gnomAD): Loss-of-function variants: 44 observed, 61.73 expected, observed/expected ratio (o/e) 0.71, 90% interval 0.56 to 0.92. The upper end of that interval is the gene's LOEUF score, 0.92, which puts it in group 3 of 6, group 1 being the genes least tolerant of losing a copy. Missense variants: 547 observed, 625.1 expected, observed/expected ratio (o/e) 0.88, 90% interval 0.81 to 0.94. Synonymous variants: 229 observed, 232.75 expected, observed/expected ratio (o/e) 0.98, 90% interval 0.88 to 1.1.
Homologues: Orthologues: chimpanzee HPX (99% identical), macaque HPX (94% identical), rat Hpx (76% identical), mouse Hpx (74% identical), guinea pig HPX (74% identical), pig HPX (73% identical), tropical clawed frog hpx (39% identical), Caenorhabditis elegans zmp-4 (16% identical), zebrafish hpxb (13% identical), Caenorhabditis elegans zmp-3 (12% identical), Caenorhabditis elegans W01F3.2 (10% identical), Caenorhabditis elegans K03B8.6 (10% identical), and 1 more. Paralogues in human: MMP13 (18% identical), MMP25 (18% identical), MMP2 (18% identical), MMP3 (18% identical), MMP15 (17% identical), MMP16 (17% identical), MMP24 (17% identical), MMP8 (17% identical), MMP9 (17% identical), MMP10 (17% identical), MMP14 (17% identical), MMP20 (17% identical), and 11 more.
Diseases named in the same sentence as HPX in open-access papers:
HPX is named in the same sentence as 158 diseases in open-access papers, as found by Europe PMC text mining. Sharing a sentence is not in itself a finding about the gene and the disease. The quoted sentences say what the papers report.
Sepsis (19 papers, 2012 to 2025). Sepsis is defined as life-threatening organ dysfunction caused by a dysregulated host response to infection. "Enhanced HPX expression significantly reduced circulating free heme levels and bacterial loads, alleviated sepsis induced Kupffer cell loss and senescence, and improved survival in both young and aged mice." (PMID 40221420, 2025). "Severe sepsis is associated with reduced plasma concentrations of hemopexin, the top heme-binding protein." (PMID 38562925, 2024). "Hemopexin has been associated with acute inflammatory states such as sepsis and has been considered a potential therapeutic candidate to reduce morbidity and mortality in such conditions (Schaer, Vinchi, Ingoglia, Tolosano & Buehler, 2014)." (PMID 29399943, 2018). "Decreased levels of haptoglobin, hemopexin, and heme oxygenase-1 occur in critical illness, including patients with sepsis and ARDS, and decreased levels have been associated with poor clinical outcomes." (PMID 26933497, 2015). "In critically ill patients with sepsis, increased plasma haptoglobin and hemopexin levels were associated with a reduction in in-hospital mortality." (PMID 24225252, 2013). "•Increased plasma levels of haptoglobin and hemopexin measured early in sepsis are associated with decreased in-hospital mortality." (PMID 24225252, 2013). "Past human studies of haptoglobin and hemopexin have focused on their properties as acute-phase reactants and as a response to the underlying inflammation associated with sepsis." (PMID 24225252, 2013). "Thus, HPX has been linked in a co-expression protein network with vimentin in patients diagnosed with sepsis and septic shock." (PMID 31554244, 2019). "Hemopexin is a positive acute-phase reactant that plays a protective role in lipid peroxidation through its heme binding effect, its levels being negatively associated with the severity of chronic sepsis." (PMID 26633942, 2015). "Specifically, it is unknown whether haptoglobin and hemopexin levels are only a marker of illness or if elevations in sepsis have a protective function and are associated with improved outcomes independent of severity of illness and cell-free hemoglobin levels." (PMID 24225252, 2013). "We conducted a retrospective cohort study to test the hypothesis that higher plasma concentrations of haptoglobin and hemopexin in adults with sepsis are associated with a decreased risk of in-hospital mortality, independent of severity of illness and cell-free hemoglobin levels." (PMID 24225252, 2013). "Previous studies have demonstrated a relationship between haptoglobin and hemopexin concentrations and clinical outcomes in patients with sepsis." (PMID 40429487, 2025). "In sepsis-related hemolysis, hemopexin plays a similarly critical sequestering role by binding free heme, which is released from oxidized cell-free hemoglobin." (PMID 40429487, 2025). "In many heme overload-driven conditions, such as sickle cell disease, transfusion-induced hemolysis, and sepsis, endogenous HPX levels are often insufficient to provide protection." (PMID 38022615, 2023). "Evidence from both clinical and animal studies shows that HPX has potential as a biomarker in sepsis, as reviewed previously." (PMID 31554244, 2019). "These clinical sepsis data showing that low HPX predicts a poor prognosis provide a rationale for investigating the role of HPX infusions as a therapy for HPX deficiency states secondary to sepsis-induced hemolysis." (PMID 26175690, 2015). "In a separate animal model of sepsis, CFH was found to be elevated and associated with hepatic and renal injury; supplementation with hemopexin to target free heme reversed the effects of CFH in these animals." (PMID 26933497, 2015). "In animal models of sepsis, supplementation with haptoglobin or hemopexin decreases biomarkers of inflammation, reduces the incidence of acute lung injury, improves organ function, and decreases mortality." (PMID 24225252, 2013).
Sepsis (continued). "We sought to determine the association of plasma levels of endogenous free hemoglobin and haptoglobin and hemopexin with in-hospital mortality in adults with sepsis." (PMID 24225252, 2013). "Furthermore, we show that hemopexin, a heme scavenger, effectively mitigates sepsis-induced Kupffer cell death and senescence, enhances bacterial clearance, and improves survival outcomes in both young and aged mice." (PMID 40221420, 2025). "Furthermore, our in vivo studies show that increased expression of hemopexin, a heme scavenger, significantly alleviates sepsis-induced Kupffer cell death and senescence, improving survival outcomes in both young and aged mice." (PMID 40221420, 2025). "In addition, the increased levels of HPX have been reported as a protective response of ill patients to the acute phase of acute inflammatory disease, which is induced by sepsis." (PMID 40238755, 2025). "Notably, aged mice also demonstrated a 66% reduction in HPX expression in response to sepsis compared to young mice." (PMID 40221420, 2025). "Finally, sequestering heme through hemopexin suppressed the development of severe sepsis in wild-type mice exposed to a microbial infection." (PMID 37237940, 2023). "It is possible, therefore, that the differently expressed APR proteins (Hemopexin, ApoA1, and Cluster of Alpha-2-macroglobulin) found in this study might be indicators of brain damage in the sepsis model." (PMID 36600206, 2023). "Sepsis-specific treatments have been overall disappointing; however, evidence from mice supports that plasma protein therapies with HPX and /or Hp could be helpful in reducing the severity of illness and mortality." (PMID 26175690, 2015). "Thus, in the presence of a high human immunodeficiency virus (HIV) load HPX was depleted in a patient who presented with symptoms of severe sepsis or hemo-phagocytic syndrome." (PMID 26175690, 2015). "•Haptoglobin and hemopexin may only provide protection in patients with sepsis in the setting of elevated cell-free hemoglobin levels." (PMID 24225252, 2013). "Further, the lethal outcome of septic shock in patients was associated with reduced levels of serum HPX concentrations, suggesting that targeting free heme by modulation of HPX might be used therapeutically to treat severe sepsis." (PMID 22518295, 2012). "Hemopexin levels have been implicated as protective in a previous study with this model of sepsis but were not apparently affected by the loss of FtH in the myeloid cells (perhaps due in part to the wide range of individual values among the mice compared with those of Hp)." (PMID 31554244, 2019). "Plasma levels of cell-free hemoglobin are associated with mortality in patients with sepsis; however descriptions of independent associations with free hemoglobin and free heme scavengers, haptoglobin and hemopexin, are lacking beyond their description as acute phase reactants." (PMID 24225252, 2013). "Haptoglobin and hemopexin are endogenous scavengers of cell-free hemoglobin and cell-free heme, respectively, and have been shown in animals and humans to attenuate oxidant injury and to reduce inflammation, acute lung injury, and mortality in animals with sepsis." (PMID 24225252, 2013). "Therefore, in a clinical setting, monitoring the patients' levels of circulating heme and/or HPX might be used to predict the likelihood of a fatal outcome in each case of severe sepsis." (PMID 22518295, 2012). "In addition, the effects of free hemoglobin in experimental sepsis can be inhibited by hemopexin." (PMID 22800762, 2012). "HPX has been evaluated as a therapeutic agent in various heme overload diseases, including SCD, blood transfusions, sepsis, malaria, hemolytic-uremic syndrome, ICH, and SAH." (PMID 38022615, 2023). "Because heme toxicity is the impetus for much of the pathology in sepsis, sickle cell disease (SCD), and other hemolytic conditions, the biological importance and clinical relevance of HPX, the predominant heme binding protein, is reinforced." (PMID 26175690, 2015).
Sepsis (continued). "To assess whether increasing HPX expression could mitigate sepsis severity, we administered AAV-HPX, with AAV-Con as a control." (PMID 40221420, 2025). "It has been found that the concentrations of hemopexin in the plasma of non-survivors are significantly lower than those in survivors with sepsis." (PMID 38022615, 2023). "There has been evidence, some published over 35 years ago, that a lack of plasma HPX, or the presence of heme-HPX with methemalbumin, is an ominous prognosis in sepsis, as well as hemorrhagic shock and liver cirrhosis." (PMID 26175690, 2015). "Additionally, in experimental animal models of sepsis, blocking the deleterious effects of CFH with the heme-binding protein hemopexin resulted in reduced organ injury and mortality." (PMID 26933497, 2015). "Notably, HPX expression is upregulated during sepsis, and survivors exhibit higher HPX levels compared to non-survivors, suggesting a protective role of HPX in sepsis outcomes." (PMID 40221420, 2025).
sickle cell disease (15 papers, 2012 to 2024). Sickle cell anemias are chronic hemolytic diseases that may induce three types of acute accidents: severe anemia, severe bacterial infections, and ischemic vasoocclusive accidents (VOA) caused by sickle-shaped red blood cells obstructing small blood vessels and capillaries. "In this review, we outline the current research regarding how the dynamic activity of hemopexin is implicated in sickle cell disease, which is characterized by a pathological aggregation of red blood cells and excessive hemolysis." (PMID 34203861, 2021). "Previous reports from patients with sickle cell disease, spherocytosis, autoimmune hemolytic anemia, erythropoietic protoporphyria and pyruvate kinase deficiency suggest that Hp depletion in plasma occurs prior to the decline of hemopexin (Hx) concentrations." (PMID 25389409, 2014). "Chronic hemolysis in sickle cell disease reduced the heme transport protein hemopexin and increased heme in circulation induced oxidative stress." (PMID 39197168, 2024). "Heme was found to strongly contribute to the pathogenesis of sickle cell disease, whereas hemopexin and HO-1 protect against heme-induced detrimental effects." (PMID 33414780, 2020). "To further address the mechanism, we used a hyperhemolytic murine model (Townes-SS) of sickle cell disease to examine cellular responses to haptoglobin and hemopexin supplementation." (PMID 29694434, 2018). "A later report showed that both HPX and Hp are depleted in sickle cell anemia, sickle cell-HbC disease or thalassemia major." (PMID 26175690, 2015). "The levels of the hemoglobin and heme scavengers haptoglobin and hemopexin drastically drop in malaria, thalassemia and sickle cell disease which confirm accumulation of free heme in all these conditions albeit their distinct kinetics." (PMID 23029401, 2012). "In summary, the current research indicates that hemopexin is likely protective against these symptoms and that rectifying depleted hemopexin in patients with sickle cell disease could improve or prevent the symptoms." (PMID 34203861, 2021). "The data compiled in this review suggest that further preclinical and clinical research should be conducted to uncover pathways of hemopexin in pathological states to evaluate its potential clinical function as both a biomarker and therapy for sickle cell disease and related hemoglobinopathies." (PMID 34203861, 2021). "The heme scavenger protein hemopexin has been efficient in preventing hemolysis-mediated C3 deposition in kidneys in a mouse model of intravascular hemolysis and on endothelial cells in vitro, as well as in models of stasis in sickle cell disease or other hemolytic conditions." (PMID 30619356, 2018).
malaria (11 papers, 2012 to 2024). Malaria is a serious and sometimes fatal disease caused by a parasite that commonly infects a certain type of mosquito which feeds on humans. "The protective effect exerted by HP and HPX against sterile intravascular hemolysis in mice led us to hypothesize that HP and HPX may be protective against malaria-associated intravascular hemolysis." (PMID 38307624, 2024). "Whereas HP and HPX exert some level of control over the pathogenic effects of labile heme, other serum heme-binding proteins and/or macromolecules might partake in this defense mechanism that establishes disease tolerance to malaria." (PMID 38307624, 2024). "To further understand the age-dependent protective effect of HP and HPX against malaria AKI, we compared bulk RNAseq data from adult versus ageing naïve and Pcc-infected Hp+/+Hpx+/+ mice." (PMID 38307624, 2024). "This suggests that in adult mice the accumulation of labile heme in serum during malaria is controlled by HP and HPX." (PMID 38307624, 2024). "This suggests that HP and HPX limit the accumulation of heme–iron in the kidneys of ageing mice, a major driving force in the pathogenesis of malaria AKI." (PMID 38307624, 2024). "In conclusion, HP and HPX act in an age-dependent manner to prevent the pathogenesis of severe presentation of malaria in mice and presumably in humans." (PMID 38307624, 2024). "Neither HP, HPX nor labile heme interfere with parasite burden, suggesting that the HP/HB and HPX/heme scavenging systems contribute to the establishment of disease tolerance to malaria." (PMID 38307624, 2024). "In the case of malaria, the heme to HPX ratio negatively correlated with disease severity, as estimated by severe anemia, respiratory distress, stage 3 acute kidney injury, and the 6-month mortality rate." (PMID 38022615, 2023). "SAA, Apo E, Apo A1 and HPX exhibited similar trends of differential abundance in malaria and DF patients (compared to HC); however, the levels of their dysregulation were found to be much higher in the malaria patients." (PMID 28667326, 2017). "Given our findings on the heme/hemopexin balance that influences cytokine profiles during severe malaria, we first investigated a possible correlation between EPO, TNF-α, IL-10, IP-10 and MCP-1 plasma levels." (PMID 27441662, 2016). "Under homeostasis, HPX can scavenge most of the free heme to form heme-HPX complex which prevent the onset of malaria." (PMID 25656928, 2015). "Many studies have expressed concerns about the deleterious effects of HE in the pathogenesis of malaria, especially since plasma hemopexin is known to be depleted in severe human malarial infection." (PMID 26465787, 2015). "The expression of HPX has also been identified in several malaria studies, where this protein provides the support line of defence against haemoglobin-mediated oxidative damage during intravascular haemolysis." (PMID 25656928, 2015). "Another potential therapy would involve the use of hemopexin or haptoglobin in adjunctive therapies capable of quenching excessive free heme in malaria patients." (PMID 26555697, 2015). "The significant increase in plasma hemopexin found in P. c. adami infected mice suggests a difference in its induction pathway in mice and humans, since pronounced exhaustion of hemopexin occurs during human malaria." (PMID 26465787, 2015). "Hemopexin is the most important scavenger of free heme, and its levels decrease in hemolytic pathologies including malaria." (PMID 23358441, 2013). "This suggests that a fraction of the heme released from damaged RBC might “escape” HPX, presumably therefore contributing to the pathogenesis of severe presentations of malaria, as demonstrated for experimental CM in mice." (PMID 38307624, 2024). "This suggests that HP and HPX control systemic iron metabolism during malaria in adult mice." (PMID 38307624, 2024).